MPC1 (mitochondrial pyruvate carrier 1)
Diseases named in the same sentence as MPC1 in open-access papers (continued):
Sharing a sentence is not in itself a finding about the gene and the disease.
breast tumors (1 paper, 2018). "Altogether, a shifted MPC2/MPC1 ratio in breast tumors may have an impact on respiratory metabolism which could lead to increase in the mitochondrial pyruvate oxidative metabolism." (PMID 29472561, 2018).
cardiac hypertrophy (1 paper, 2021). "Downregulation of MPC1 and MPC2 was observed in failing human hearts and in mouse models of pathological cardiac hypertrophy." (PMID 33473180, 2021).
cognitive deficits (1 paper, 2020). "The patient with the MPC1 R97W mutation died at 19 months, while three patients with the MPC1 L79H mutation exhibited varying degrees of neurological and cognitive deficits." (PMID 32784379, 2020).
colon adenocarcinoma (1 paper, 2017). "Consistent with our previous data, we found that mpc1 expression is significantly downregulated in colon adenocarcinomas with APC deletions (n = 91) compared to normal colon (n = 19)." (PMID 28397687, 2017). "Recent studies have shown that mitochondrial pyruvate carrier 1 (MPC1), a crucial player in pyruvate metabolism, is downregulated in colon adenocarcinomas." (PMID 28397687, 2017). "We also looked at other genes involved in pyruvate transport and metabolism and interestingly, MPC1, MPC2, PDHA1 and PC showed consistent downregulation in a specific subset of colon adenocarcinomas known as colon mucinous adenocarcinomas (AC) (n = 22)." (PMID 28397687, 2017).
developmental delay (1 paper, 2024). "In addition, MPC deficiency due to pathogenic MPC1 gene variants is a rare autosomal recessive disorder involving developmental delay and microcephaly." (PMID 38243137, 2024).
diabetic nephropathy (1 paper, 2020). "Renal tubule MPC1 and MPC2 protein expression were significantly lower in diabetic nephropathy patients compared to patients with non-diabetic kidney disease." (PMID 32784379, 2020).
epilepsy (1 paper, 2022). A brain disorder characterized by episodes of abnormally increased neuronal discharge resulting in transient episodes of sensory or motor neurological dysfunction, or psychic dysfunction. "The MAS/MPC1- defects are a group of rare diseases with either a neurological phenotype with early onset epilepsy, muscle hypotonia and a severe global developmental impairment or a hepatopathy (citrin deficiency)." (PMID 36079864, 2022).
esophageal squamous cell carcinoma (1 paper, 2017). Esophageal squamous cell carcinoma (ESCC) is a type of esophageal carcinoma (EC) that can affect any part of the esophagus, but is usually located in the upper or middle third. "In addition, we also determined the expression status of MPC1 and MPC2 in a series of 157 esophageal squamous cell carcinomas and found that the low expression of MPC1 predicted an unfavorable outcome, indicating the regulation of metabolic reprogramming by MPC1 is pivotal for tumor cell growth." (PMID 27911865, 2017).
gastric tumors (1 paper, 2025). "Reduced MPC1 levels in gastric tumors are associated with a more severe disease course." (PMID 39920561, 2025).
Hepatic steatosis (1 paper, 2024). Steatosis is a term used to denote lipid accumulation within hepatocytes. "The upregulated mitochondrial protein OPA3 is a crucial regulator of mitochondrial function, whereas the expression levels of ACSL1 and MPC1 are directly correlated with hepatic steatosis." (PMID 39280921, 2024).
Hyperglycemia (1 paper, 2019). An increased concentration of glucose in the blood. "Constitutive hepatic MPC1 deletion attenuated the development of hyperglycemia induced by a high-fat diet." (PMID 31540439, 2019). "Even acute MPC1 deletion in hepatocytes (in MPC floxed (MPC1fl/fl) littermates treated with AAV-Cre driven by a hepatocyte-specific promoter) after diet-induced obesity decreased hyperglycemia and improved glucose tolerance." (PMID 31540439, 2019).
hypertrophic cardiomyopathy (1 paper, 2024). A condition in which the myocardium is hypertrophied without an obvious cause. "Our group and others recently discovered that mice subjected to inducible heart-specific deletion of Mpc1 spontaneously develop hypertrophic cardiomyopathy, become moribund, and perish 16 weeks after induction due to HF symptoms." (PMID 39052437, 2024).
Impaired glucose tolerance (1 paper, 2024). An abnormal resistance to glucose, i.e., a reduction in the ability to maintain glucose levels in the blood stream within normal limits following oral or intravenous administration of glucose. "Similarly, MPC1 protein expression was reduced in subcutaneous WAT from female (but not male) prediabetic human subjects displaying impaired fasting glucose, impaired glucose tolerance, and impaired adipose function compared to control subjects with normal glucose tolerance." (PMID 39137831, 2024).
liver fibrosis (1 paper, 2024). "It has been reported in the liver that mitochondrial pyruvate carrier 1 (MPC1) regulates fatty acid synthase lactylation, affecting both liver fibrosis and nonalcoholic fatty liver." (PMID 38202819, 2024).
lymph node metastasis (1 paper, 2016). "Our study shows that tumor tissue MPC2 expression is inversely correlated with the following PCA clinicopathologic characteristics like UICC stage and lymph node metastasis, while MPC1 expression is inversely correlated with the UICC stage." (PMID 27852261, 2016).
malaria (1 paper, 2024). Malaria is a serious and sometimes fatal disease caused by a parasite that commonly infects a certain type of mosquito which feeds on humans. "A previous study demonstrated that artemether (Art), an artemisinin derivative applied in the treatment option for malaria, could protect against kidney injury in T2D db/db mice partially via increasing MPC1 and MPC2 levels." (PMID 39247825, 2024).
migraine (1 paper, 2022). "The most correlations between cytokines are in migraine patients only without aura, such as correlations between MPC-1 and PAI-1 (direct correlation), MMP-9 (direct), sICAM-1 (inverse), and sVCAM-1 (inverse)." (PMID 36233564, 2022).
non-small cell lung carcinoma (1 paper, 2025). A group of at least three distinct histological types of lung cancer, including non-small cell squamous cell carcinoma, adenocarcinoma, and large cell carcinoma. "Correlational analysis of the MPC1 gene in human lung, hippocampus and frontal cortex tissue samples based on data from the GTEx database revealed associations of this gene with schizophrenia, non-small cell lung cancer, and immune diseases." (PMID 39920561, 2025). "Our experiments showed that the mRNA level of the MPC1 gene in the non-small cell lung cancer cell line A549 increases 5-fold under the influence of the schizophrenia neuroleptic thioridazine." (PMID 39920561, 2025).
osteosarcoma (1 paper, 2023). A usually aggressive malignant bone-forming mesenchymal neoplasm, predominantly affecting adolescents and young adults. "This clustering of the osteosarcoma microenvironment fraction in mice and patients is driven by the MPC1, and is identified as the regulation of the immune response by functional enrichment analysis." (PMID 37723198, 2023).
pancreatic adenocarcinoma (1 paper, 2021). "The results indicated that MPC1 was significantly differentially expressed in many cancers, such as BRCA, KIRC, LUAD, pancreatic adenocarcinoma (PAAD), and PRAD." (PMID 34059057, 2021).
Renal cyst (1 paper, 2024). A fluid filled sac in the kidney. "On the other hand, the MPC1 (−1.5×)/MPC2 (−2.1×) heterodimer responsible for transporting pyruvate into the mitochondria for ATP production was downregulated in renal cysts." (PMID 39000280, 2024).
retinal degeneration (1 paper, 2021). Degeneration of the retina. "Furthermore, retina-specific deletion of MPC1 resulted in progressive retinal degeneration and decline of visual function in photoreceptors." (PMID 33923192, 2021).
Sepsis (1 paper, 2025). Sepsis is defined as life-threatening organ dysfunction caused by a dysregulated host response to infection. "Gene expression of lactate dehydrogenase (Ldhb) and of the mitochondrial pyruvate carriers (Mpc1 and Mpc2) was also not affected by sepsis." (PMID 39821755, 2025).
thymoma (1 paper, 2021). A neoplasm arising from the epithelial cells of the thymus. "In addition, in HNSC, LUSC, ovarian cancer (OV), thymoma (THYM), THCA, and tenosynovial giant cell tumour (TGCT), there were strong correlations between the immune cell infiltration level and MPC1 expression." (PMID 34059057, 2021). "MPC1 expression shows strong positive and negative correlations with immune cell infiltration in thymoma (THYM) and thyroid carcinoma (THCA)." (PMID 34059057, 2021).
tumor (55 papers, 2016 to 2026). "Protein level analyses revealed lower MPC1 protein levels in basal-like PDAC cases and association of low MPC1 levels with clinicopathologic parameters of tumor aggressiveness in PDAC." (PMID 39363341, 2024). "Consistent with previous studies, the average weight and volume of RCC xenograft tumours in the MPC1-deficient groups were significantly greater than those in the MPC1 overexpression groups." (PMID 34059057, 2021). "In ICC tissues, the expression of MPC1 as measured by immunohistochemistry is lower than that in non-tumour tissues, a finding that is closely associated with poor prognosis." (PMID 34059057, 2021). "Lower MPC1 expression is associated with advanced tumour stage, greater invasion depth, and lymph node metastasis." (PMID 34059057, 2021). "qPCR analysis of normal adjacent and paired tumor tissue confirmed Mpc1 expression loss in MPC LivKO mice." (PMID 31484072, 2019). "MPC1 expression was significantly associated with the depth of tumor invasion, clinical stage and distant metastasis of ESCC." (PMID 27911865, 2017). "MPC-1 is a protein secreted by the infiltrated inflammatory cells and associated with the maturation and attraction of tumor-associated macrophages (TAMs)." (PMID 28207826, 2017). "The observed elevation of MPC1 level may cause tumor infiltration by immune cells, complementing the previously reported data indicating the ability of thioridazine to slow cell growth, induce apoptosis and reduce the ability of cells to migrate." (PMID 39920561, 2025). "Moreover, the expression level of MPC-1 was also negatively associated with lager tumor size and lymph nodes metastasis." (PMID 38615083, 2024). "However, only WT cells were able to partially rescue mTOR activity when lactate was included in the culture, reflecting the loss of mTOR activity specifically in tumor-infiltrating MPC1 KO CD8+ T cells in vivo." (PMID 35452600, 2022). "Therefore, reduced expression of MPC1 is associated with increased glycolytic activity in tumors and thus promoting tumor development, which is consistent with our findings above." (PMID 34030708, 2021). "MPC1 gene expression is downregulated in most tumor types, excluding hematologic malignancies, leukemia, and lymphoma." (PMID 40746885, 2025). "Specifically, MPC1 knockdown has been shown to increase glycolytic levels and cell invasion in tumor cells, highlighting its pivotal role in regulating tumor cell growth." (PMID 40332105, 2025). "Further studies examining MPC1 expression in LAC tissues compared to versus adjacent non-tumor tissues corroborate these findings." (PMID 39179991, 2024). "A decrease in MPC activity, driven by reduced expression of MPC1, promotes glycolysis and tumor progression in several cancer types." (PMID 39363341, 2024). "Prognostic relevance of MPC1 was determined using a tumor tissue microarray (TMA) in resectable, and proteomics profiling in metastatic PDAC datasets." (PMID 39363341, 2024). "MPC1's role in enhancing pyruvate entry into mitochondrial oxidation and reducing lactate production in tumor cells suggests its impact on tumor cell invasion and metastasis." (PMID 39179991, 2024). "MS-based proteomic profiling of tumor tissue samples (n = 45) demonstrated lower levels of both MPC subunits MPC1 (p = 0.024) and MPC2 (p = 0.018) in basal-like tumors." (PMID 39363341, 2024). "The expression of MPC1 is decreased in most tumor types, especially those under a high proliferation rate related to the increased rate of glycolysis." (PMID 36207479, 2023). "Of note, the deregulation of PDK1, TIGAR, and MPC1 was previously strongly correlated with tumor development." (PMID 37508533, 2023). "Using patient tumor microarray data (GSE10846), we found that the mRNA levels of MPC1 and MPC2, the genes that encode the MPC1 and MPC2 subunits of the MPC, were higher in OxPhos-DLBCLs." (PMID 36179030, 2022).
tumor (continued). "As in the in vivo tumor microenvironment, MPC1 KO CD8+ T cells in nutrient-deprived conditions were as viable as WT T cells." (PMID 35452600, 2022). "Tumor cells are sensitive to MPC1 expression, because of their high intracellular iron levels and increased oxidative stress compared to normal cells." (PMID 36009223, 2022). "MPC1 deletion promotes tumour initiation as well as a proliferative and protumorigenic phenotype in genetic tumour models." (PMID 34059057, 2021). "MPC1 is downregulated in many tumour cells, which affects tumour mitochondrial respiratory capacity." (PMID 34059057, 2021). "LUAD cell lines with lentiviral vector-mediated MPC1 overexpression exhibited smaller volumes and numbers of tumour spheres." (PMID 34059057, 2021). "They used xenografts to validate that reintroduction of appropriate MPC1 expression reduces tumour growth." (PMID 34059057, 2021). "In mouse xenograft tumours, the overexpression of MPC1 reduces the tumour growth rate and tumour size." (PMID 34059057, 2021). "The overexpression of MPC1 in CRC significantly inhibits the stemness and proliferation abilities of tumour suppressor-deficient intestinal stem cells." (PMID 34059057, 2021). "Decreasing the expression of MPC1, like MPC1 knockdown and MPC1 silencing, resulted in significantly increased tumour size and volume." (PMID 34059057, 2021). "For instance, MPC1 inhibitors trigger local reoxygenation that sensitizes tumor xenografts to radiotherapy." (PMID 33804985, 2021). "Targeted deletion of MPC1 in adult LRIG1+ intestinal stem cells (Mpc1Lrig1KO) led to an increased tumor burden and a substantial increase in the incidence of macroscopic tumors in the AOM-DSS model." (PMID 32708919, 2020). "Conversely, in a Drosophila hyperproliferation model, overexpression of Mpc1 in intestinal stem cells was sufficient to prevent tumor formation." (PMID 32784379, 2020). "Collectively, these findings indicate that MPC1 probably serves as a tumor suppressor to impair tumor malignancy." (PMID 30770798, 2019). "Mitochondrial pyruvate carrier 1 (MPC1), a key factor that controls pyruvate transportation in the mitochondria, is known to be frequently dysregulated in tumor initiation and progression." (PMID 30770798, 2019). "Despite the involvement of MPC1 in tumor progression, the clinical relevance and function of MPC1 in LAC remains to be investigated." (PMID 30770798, 2019). "Linear regression analysis further revealed that the MPC1 expression was positively correlated with the MPC2 expression in the PCA tumor tissues (r = 0.348, P =0.017)." (PMID 27852261, 2016). "Another tumor suppressor, mitochondrial pyruvate carrier 1 (MPC1), is also regulated by PGC1α." (PMID 38774408, 2024). "This may be because the deeper the tumor’s infiltration depth would result in the lower expression of a protein called MPC1." (PMID 39703842, 2024). "The higher sensitivity to UK-5099 observed in the basal-like tumor derived PCBC-015 suggests that this PDO may have greater reliance on pyruvate from glycolysis to feed the TCA cycle and is more susceptible to MPC1 inhibition." (PMID 39363341, 2024). "Tumors with a ‘glycolytic’ gene profile had the worst prognosis and exhibited lower MPC1 expression, suggesting that specific tumor metabolic pathways may contribute to prognostic differences between PDAC subtypes." (PMID 39363341, 2024). "Lower response to MPC1 inhibition in the Seahorse and 13C-glucose tracing experiments suggests that classical tumor PDOs may use an alternative transport pathway for TCA cycle intermediates." (PMID 39363341, 2024). "Hence, inhibition of MPC1 resulted in a small increase in glycolytic activity in PDOs from both tumor subtypes and attenuated OCR in basal-like PDOs to levels similar to classical PDOs under non-treated conditions." (PMID 39363341, 2024). "MPC1 affects cancer progression by regulating tumorigenicity, tumor stemness, and chemoresistance." (PMID 36902385, 2023).